CD40 (CD40 molecule)
Diseases named in the same sentence as CD40 in open-access papers (continued):
Sharing a sentence is not in itself a finding about the gene and the disease.
tumor (continued). "Intriguingly, serum levels of sCD40L were inversely correlated with LMP-1 expression by tumor cells, suggesting that LMP-1-negative UNPC cells may require CD40 activation for growth and/or survival." (PMID 17331231, 2007). "CD40 is a 48 kDa membrane glycoprotein of the tumour necrosis factor receptor (TNFR)/nerve growth factor superfamily, and is expressed on the surface of B lymphocytes, dendritic cells, epithelial and haemopoietic stem cells, and various tumours." (PMID 12592374, 2003). "It includes CD40 agonists, CSF-1R inhibitors, CD11b agonists, CCR2 inhibitors, BTK inhibitors, and emerging chemokine receptor inhibitors, such as CXCR2 and CXCR4 antagonists, highlighting the diverse immune modulating approaches to reprogram the immunosuppressive tumor microenvironment." (PMID 40458409, 2025). "KCNN4 has been shown to have positive correlations with several costimulatory molecules (CD276, CD40, CD70, CD80, CD86), immune signaling receptors (IL2RA, MICB, NT5E), and multiple TNFRSF family members, suggesting its involvement in immune modulation, inflammation, and tumor‐immune interactions." (PMID 40952239, 2025). "TZ‐dSA3‐12‐treated E0771‐HER2 cancer cells markedly increased the surface expression of activation markers, including CD40, CD80, CD86, MHC‐I, and MHC‐II on bone marrow‐derived dendritic cells (BMDCs), suggesting that TZ‐dSA3‐12‐treated tumor cells enhance the antigen presentation capacity of DCs." (PMID 40492586, 2025). "Indeed, surrounding environmental cells such as mesenchymal stromal cells (MSCs), nurse-like cells (NLCs), and macrophages, and different signaling pathways including the BCR signaling pathway and CD40/CD40L, play an important role in the survival and the proliferation of CLL tumor cells." (PMID 40864758, 2025). "This may be explained by the fact that Gal-9 released from tumor cells suppresses anti-tumor immunity by interacting with various surface receptors including TIM-3, PD-1, VISTA, CD40, CD44 and DR3 in T lymphocytes, leading to T cell exhaustions and immune tolerance." (PMID 40138336, 2025). "Therefore, since CD40-mediated ICS induces T cell priming, agonistic CD40 antibodies should rather be used in combination regimen that offer tumour specific antigens as T cell targets or alleviate T cell suppression, like vaccination approaches or ICI respectively." (PMID 38440738, 2024). "A recent study also confirmed that the addition of CD40 antibody to irreversible electroporation (IRE) could improve DC activation and neoantigen recognition in a mouse model, while generating a strong systemic anti-tumor T cell response." (PMID 38167055, 2024). "Furthermore, as a single agent, it exhibited anti-tumor activity in a colorectal cancer mouse model (CD40-negative syngeneic MC38-CEA)." (PMID 39120299, 2024). "It is most likely that the activated DCs in the MBTA alone group result from the immune‐activating effects of Mannan, TLR agonists and CD40 agonistic antibody, leading to their migration to the draining LN where they activate T cells that are not specific to the tumor." (PMID 38298111, 2024). "Moreover, the population of F4/80+CD40+ macrophages increased in spleen of these groups; whereas, the difference in the tumor was not significant." (PMID 38630304, 2024). "However, some current studies showed that CD40 activation-mediated tumor regression was independent of T cells." (PMID 38008741, 2023). "Refractory effector T cells in the TME can be revitalized to regain their anti-tumor activities, i.e., the ability to restrain tumor growth, by stimulating T cell costimulatory receptors, such as those belonging to the tumor necrosis factor receptor superfamily (TNFRSF), i.e., CD40, 4-1BB, and OX40." (PMID 38140230, 2023). "Further, it was shown that CD40 expression alone on cDC1 results in a more robust expansion of antigen-specific CD8+ T cells, further evidence that increased expression of CD40 might directly impact priming of tumor-reactive T cells." (PMID 37548358, 2023).
tumor (continued). "The upregulation of CD1C, CD40, CD80, and CD86 on Bregs shown in our study indicated that Bregs might exhibit a strong ability of antigen presentation in the MPE immune microenvironment in vivo due to tumor antigen stimulation." (PMID 37432957, 2023). "Another immunologically important molecule is CD40, which is a member of the TNF receptor family, and a co-stimulatory cell surface receptor, expressed by APCs, other non-immune cells (e.g., epithelial and endothelial cells, platelets, fibroblasts, etc.)and tumor cells." (PMID 37243029, 2023). "In addition to the CD47/SIRPα cascade, CD40 agonists re-educate TAMs into M1 macrophages to restore cancer immune surveillance, and the combination therapy of anti-PD1/PD-L1 and anti-CD40 also enhances anti-tumor efficacy." (PMID 36845095, 2023). "Additionally, targeting CD40 in immunotherapy has been suggested to play a crucial role in remodeling the TME, especially via the repolarization of macrophages, leading to the degradation of tumor stroma by altering the expression of metalloproteases." (PMID 37830579, 2023). "Next, to determine if RT+CTLA4i+anti-CD40 could induce responses against a non-irradiated tumor (abscopal response), mice were implanted with AT3 cells in both flanks, with radiation delivered only to one of the two tumors." (PMID 37620372, 2023). "Taken together, these results strongly suggest that the main effect of anti-CD40 in 4T1 tumors is to increase cDC1, promote their activation and migration to dLN where they cross-present tumor antigens to CD8 T cells, whereas RT reduces the presence of immunosuppressive macrophages in the tumor." (PMID 37620372, 2023). "Furthermore, while CD40 expression by tumor cells seems to be common, it has not been assessed quantitatively or in large populations." (PMID 36894898, 2023). "Consistently, our data show that anti-CD40 main effect was to activate cross-presenting DCs at the irradiated tumor site and draining lymph node and promote the expansion of tumor-specific CD8+ T cells migrating between the dLN and the tumor in mice treated with RT+CTLA4i." (PMID 37620372, 2023). "The higher expression of the co-stimulatory molecule and M1 marker CD40 on CD45/CD14+ cells in the 4-culture PANC-1 spheroids could explain the therapeutic effect of CD40 ligand/agonists in the treatment of PDAC, boosting an anti-tumor response." (PMID 37519820, 2023). "It was found that agonistic anti-CD40 antibodies could stimulate TAMs to promote the secretion of the proinflammatory cytokines such as NO and TNF-α to activate effector T cells to reestablish tumor immune surveillance." (PMID 36816959, 2023). "Furthermore, LPS induces the expression of the CD40 gene, which is a member of the TNFR family and is mainly expressed by cells such as macrophages, microglia, and dendritic cells as well as endothelial and tumor cells." (PMID 37110573, 2023). "In the draining lymph nodes (TdLNs) of an MC38 model, a radioimmunogenic tumor-bearing mouse model, RT did not change the number of tumor-migratory cDCs but promoted the maturation of DCs by upregulating the expression of the costimulatory molecules CD40 and CD80." (PMID 37208386, 2023). "In stromal-rich regions that lacked CK + tumor cells, 1045 T cells + CD40 agonist increased Cxcl9/Cxcl10 expression by macrophage and 1045 T cells appeared to colocalize with the Cxcl9 + macrophage in these stromal regions, similar to our results in resected human PDA." (PMID 36472588, 2023). "In addition, previous studies have shown that both CD40 and TNFSF14 are important tumor suppressor factors and CD40/CD40L interaction plays a critical role in the maturation of DCs in vivo, which greatly affect APC function, namely IL-12 production, in antitumor responses." (PMID 38021165, 2023).
tumor (continued). "In this context, CD40L–CD40 signaling may sustain immunosuppression and blocking CD40L–CD40 interaction with antagonistic CD40 antibodies, such as Lucatumumab, may increase the anti-tumor immune response and may be tested in combination with immunotherapy." (PMID 37038035, 2023). "Consistent with murine data, expression of HLA-DR, CD86, CD40 and PDL1 was significantly increased in CD141+ cDC1 DCs (equivalent to mouse XCR1+) and CD1c+ cDC2 DCs (equivalent to mouse CD11b+), but not in pDCs, both pre- and post-Flt3L, upon co-culture with NDV-preinfected tumor cells." (PMID 36418317, 2022). "CD40, a TNF receptor superfamily member, is expressed on APCs and is critical for their activation and proliferation, as well as an important regulator of T cell-dependent anti-tumor immunity via the interaction with CD40 ligand (CD40L) mainly expressed by CD4+ T cells." (PMID 35664746, 2022). "Therefore, it appears not unlikely that FcγR-independent CD40 agonists will also elicit dose-limiting toxicity upon systemic application thereby preventing the maximal possible CD40 activation in the tumor microenvironment." (PMID 36361658, 2022). "Therefore, advanced combination treatments including, e.g. CD40 agonists, TGFβ blockade, or therapeutics targeting KRAS signaling, the myeloid compartment, or tumor stroma may improve efficacy of virotherapy plus checkpoint blockade in PDAC." (PMID 36726983, 2022). "However, similar to the in vitro data, intratumoral cDCs showed a significant increase of MHC-I, MHC-II, and CD40 markers on tumor-infiltrating cDC1 cells lacking Siglec-E compared to cDC1 cells from littermate control mice." (PMID 35309936, 2022). "Activated M1 macrophages typically express CD40 and CD86 and secrete higher levels of proinflammatory factors than M2 macrophages, such as IL-1α, tumor necrosis factor (TNF), and IL-12, which mainly exert an antitumor immune response and directly kill tumor cells in the early stage of a tumor." (PMID 35740975, 2022). "Whether pretreatment with anti-CD40 can broaden the repertoire of T cells that can be expanded from patient tumor explants has not yet been studied." (PMID 34282297, 2022). "This situation was alleviated by vaccination with a recombinant virus expressing the targeted tumor antigen, suggesting that either virally induced inflammation or providing additional antigen was needed, as seen with the benefits of cotargeting PRR with CD40 stimulation." (PMID 34282297, 2022). "viSNE analysis revealed that NDV-killed tumor cells preferentially induced activation of Lin-I-Ad+CD11c+ conventional DCs (cDCs), as indicated by upregulation of MHC II, co-stimulatory molecules (CD86, CD40) and PDL1, with similar effects in both cross-presenting XCR1+ cDC1 and CD11b+ cDC2 subsets." (PMID 36418317, 2022). "Moreover, unlike partial blocking of tumor progression or invasive signals, CD40 agonists are “ignition” signals that promote the initiation of immune responses in PDAC, contributing to anti-tumor immunity dependent on CD8 T cells and activated antigen-presenting cells (APCs)." (PMID 36499340, 2022). "Importantly, in an ovarian cancer model, in situ co-administration of CD40 and TLR3 agonists has induced the polarization of tumor-infiltrating DCs into an immune stimulatory phenotype that was able to produce type I IFN and IL-12 p70, resulting in tumor remission." (PMID 34262904, 2021). "In addition, we found that the expression levels of T-cell exhaustion-related genes including CD40, GRB2, MKI67, NFATC3, PRDM1, TCF7, and TGFB1 were significantly higher, while those of CXCR5 and TOX were significantly lower after tumor recurrence (all p < 0.05)." (PMID 34305618, 2021). "Additionally, surface modification of nanoparticles to incorporate immune stimulation such as the use of an anti-CD40 monoclonal antibody, has been shown to induce potent CD8+ T cell responses resulting in tumour growth attenuation and prolonged survival in preclinical models." (PMID 34709394, 2021).
tumor (continued). "Interestingly, chemotherapy, when followed by CD40 agonism (but not vice versa) in murine solid tumor models, has elicited effective T cell responses, tumor clearance, and T cell memory." (PMID 34868044, 2021). "However, even in tumor-bearing mice, anti-CSF1R treatment failed to mitigate treatment-induced weight loss or transaminitis triggered by CD40 chemoimmunotherapy." (PMID 34101617, 2021). "However, the observed effect in this study was not related to a positive expression of CD40 by tumor cells." (PMID 33180184, 2021). "However, in an anti-PD-1-resistant model of MIBC, we demonstrated that anti-CD40 therapy induced an anti-PD-1 response by activating DCs in tumor-draining lymph nodes but not in the tumor." (PMID 34572939, 2021). "Interestingly, CD40 ligation leads to a positive feedback by inducing the upregulation of intracellular TLRs, resulting in synergistic activation of both anti-CD40 and TLR ligands in macrophages in several tumor mouse models." (PMID 34572013, 2021). "Yu and his colleagues also showed us anti-CD40 agonist therapy could amplify immune-activated cDC1 subset, increase effector memory CD8+ CTLs, and induce the activation and expansion of TH1-like CD4+ T cells in MC38 tumor model." (PMID 33648605, 2021). "In addition, all treatments, except for CD40 stimulation treatment alone, reduced the expression of immunosuppressive cytokines including IL-10 and TGF-β, in the tumor tissues, compared with control treatment with IgG, verifying the reversal of Mφ–mediated immune suppression in GBM." (PMID 34103524, 2021). "Of note, sample #15A which according to cytology had few intact tumor cells but a high content of mostly degenerative and inflammatory cells including macrophages (which are PD‐L1‐positive) deviated most from the correlation line for multiple markers, for example, CD4, CD5, CD40, and CD83." (PMID 33768639, 2021). "In addition to the role of HDAC inhibitors in sensitizing tumor cells to chemoradiotherapy, studies have also investigated the role of HDAC inhibitors in regulating immune-related genes, such as CD40 expression and HLA class I and II in different cancer cell lines." (PMID 34680389, 2021). "Our data showed that CD40 stimulation alone did not affect tumor growth or animal survival." (PMID 34103524, 2021). "The results showed that the risk scores were negatively associated with the expression of the critical immune checkpoints (TNFRSF14 and CD40), indicating that the poor prognosis of high IGPM patients might be due to the tumor immunosuppressive microenvironment." (PMID 33628738, 2020). "Therefore, the data indicated that the focus of CD40-stimulating anti-tumor therapies should not exclusively be on the immune compartment." (PMID 32582531, 2020). "In addition, compared to non‐tumor tissue infiltrating DCs, all tumor‐infiltrating DC subsets exhibited an increased CD80 expression together with an upregulation of CD40 for pDCs and cDC1s, while the level of CD86 was found to be downregulated on tumor‐infiltrating pDCs." (PMID 33282290, 2020). "Furthermore, when stimulated by tumor antigens, γδ T cells will up-regulate the expression of antigen-presenting molecules HLA-DR, costimulatory and adhesion molecules (CD80, CD86, CD40) and scavenger receptor CD36, which allow γδ T cells to participate in the elimination of tumor cells." (PMID 32413966, 2020). "CD40 agonist promotes the antitumor activity of a variety of immune-based therapeutic strategies and may do so by engaging DCs, promoting anti-tumor TAMs, and creating a TME that is conducive to anti-tumor cytolytic effector T cells." (PMID 33584701, 2020). "However, while agonist anti-CD40 supported cytotoxic activity of endogenous tumor-specific T cells, it failed to rescue cytotoxic function and cytokine production of infused engineered T cells." (PMID 33584701, 2020).
tumor (continued). "We demonstrated profound reduction in tumor growth and increased survival of mice with the majority of mice being cured when both agents were combined, including an unprecedented 8‐fold dose reduction of CD40 agonist without losing any efficacy." (PMID 32821382, 2020). "In addition, the CD40 agonist and Gem combination could also reverse resistance to ICI therapy via promoting the accumulation of robust antitumour CD8+ T cells in PDAC tumours." (PMID 32061257, 2020). "The authors postulated that the combination of radiotherapy and CD40 agonism was able to disrupt and re-organise the links between the innate and adaptive immune systems in a non-redundant way, hence resulting in tumours that were re-sensitised to anti-PD-1 and anti-CTLA-4 therapy." (PMID 31091774, 2019). "Additionally, we observed a significantly higher expression of activation molecules, namely, HLA-ABC, HLA-DR, CD86 and CD40, in TIL-Bs derived from tumor samples with high levels of B cells in comparison to TIL-Bs derived from Blo (< 5% of total cells) samples." (PMID 31623665, 2019). "However, despite increases in cytokine-producing CD4 and CD8 T cells following erlotinib-treatment, combination treatment with immunotherapies like anti-PD-1 or a CD40 agonist did not effectively prevent tumor relapse." (PMID 31291990, 2019). "In this model, the authors further demonstrated that, in vaccinated mice, the combination of anti-CD40 mAb and immune check point blockade using the anti-CTL-A4 mAb was able to delay tumor growth, resulting in complete regression and long-term survival of tumor-bearing mice." (PMID 30510968, 2018). "In our experimental model, we have shown that very small tumors in RAG1-/- mice did not affect APCs, since a single injection of anti-CD40, together with T cell transfer from tumor bearing donors, could protect mice from tumor growth." (PMID 29975708, 2018). "Importantly, IL-2/CD40 reduced expression of a number of regulatory markers on young and elderly TDLN CD11c+ cells including: CD73, TGF-β, CD39 and IL-10, relative to age-matched untreated tumor-bearing mice." (PMID 30560130, 2018). "CD40 is expressed by B cells, professional APCs, as well as non-immune cells and tumor cells." (PMID 30619273, 2018). "For example, anti-CD40 can be employed to enhance activation of APCs, granulocyte macrophage colony-stimulating factor (GM-CSF) can be used to increase the percentage of APCs, while anti-CTLA4 or PD-1 can act as immune checkpoint inhibitors, enhancing T cell action on the tumor cells." (PMID 28447024, 2017). "SUP3 was shown to enhance cross-presentation by CD8+ cDCs in vitro, up-regulate the expression of CD40 and CD86 co-stimulatory molecules and induce production of IL-6 and TNFα in DC, culminating in an antigen-specific CD8+ T cell response and increased immunization against tumor challenge." (PMID 29050360, 2017). "Macrophages express CD40, and the binding of CD154 activates monocytes/macrophages with essential consequences in tissue homeostasis by driving cytokine/chemokine, protease production and control of tissue clearance capacity, pathogen killing, or anti-tumor effects." (PMID 28785137, 2017). "This non-canonical pathway is the molecular basis for anti-CD40–induced repolarization of TAMs from a tumor-promoting M2 to a suppressive M1-like phenotype with upregulation of IL12, TNFα and INF-γ in KPC mice which spontaneously develop pancreatic ductal adenocarcinoma." (PMID 28467800, 2017). "CD40 is a member of the TNF receptor superfamily primarily expressed on antigen-presenting cells (APC), e.g. dendritic cells (DC), B cells and monocytes, but also found on some non-lymphoid cells such as epithelial and endothelial cells, fibroblasts, and some tumours." (PMID 28619093, 2017).